RNF19B (ring finger protein 19B)
Description:
E3 ubiquitin-protein ligase which accepts ubiquitin from E2 ubiquitin-conjugating enzymes UBE2L3 and UBE2L6 in the form of a thioester and then directly transfers the ubiquitin to targeted substrates, such as UCKL1. Involved in the cytolytic activity of natural killer cells and cytotoxic T-cells. Protects against staurosporin-induced cell death.
Synonyms: IBRDC3; NKLAM; FLJ90005
Tractability: Antibody: UniProt predicts a signal peptide or a membrane-spanning region. PROTAC: ubiquitination databases record sites on it.
Gene: Protein-coding gene on chromosome 1 (32,929,036 to 32,964,915, reverse strand). Ensembl gene ENSG00000116514.
Subcellular location: Cytoplasmic granule membrane; Endoplasmic reticulum membrane
Subcellular location (Human Protein Atlas): Cytosol
Pathways (Reactome):
Cell-Cell communication: Activation of STAT3 by cadherin engagement
Immune System: Antigen processing: Ubiquitination & Proteasome degradation
Gene Ontology:
Molecular function: protein binding; ubiquitin binding; ubiquitin protein ligase activity; ubiquitin conjugating enzyme binding; ubiquitin-protein transferase activity; zinc ion binding
Biological process: protein autoubiquitination; protein ubiquitination
Cellular component: endoplasmic reticulum; endoplasmic reticulum membrane; cytolytic granule; cytosol; ubiquitin ligase complex
Genetic constraint (gnomAD): Loss-of-function variants: 19 observed, 57.06 expected, observed/expected ratio (o/e) 0.33, 90% interval 0.23 to 0.49. The upper end of that interval is the gene's LOEUF score, 0.49, which puts it in group 2 of 6, group 1 being the genes least tolerant of losing a copy. Missense variants: 696 observed, 826.47 expected, observed/expected ratio (o/e) 0.84, 90% interval 0.79 to 0.9. Synonymous variants: 324 observed, 299.63 expected, observed/expected ratio (o/e) 1.08, 90% interval 0.99 to 1.19.
Homologues: Orthologues: macaque RNF19B (98% identical), chimpanzee RNF19B (98% identical), pig RNF19B (96% identical), rat Rnf19b (95% identical), mouse Rnf19b (94% identical), dog RNF19B (92% identical), guinea pig RNF19B (79% identical), tropical clawed frog rnf19b (68% identical), rabbit RNF19B (66% identical), zebrafish rnf19b (59% identical), Caenorhabditis elegans C17H11.6 (35% identical), Caenorhabditis elegans Y49F6B.9 (23% identical). Paralogues in human: RNF19A (55% identical), ANKIB1 (17% identical), RNF144A (12% identical), ARIH1 (12% identical), ARIH2 (11% identical), RNF144B (11% identical), RNF14 (11% identical), RNF217 (10% identical), PRKN (9% identical).
Diseases named in the same sentence as RNF19B in open-access papers:
RNF19B is named in the same sentence as 17 diseases in open-access papers, as found by Europe PMC text mining. Sharing a sentence is not in itself a finding about the gene and the disease. The quoted sentences say what the papers report.
acute myocardial infarction (1 paper, 2020). Necrosis of the myocardium, as a result of interruption of the blood supply to the area. "NKLAM (RNF19B) gene expression was also upregulated, along with other pro-inflammatory genes, in the peripheral blood of Chinese patients with acute myocardial infarction compared to healthy controls." (PMID 33192571, 2020).
gastric cancer (1 paper, 2021). A primary or metastatic malignant neoplasm involving the stomach. "Among the gastric cancer patients, all the 15 overlapping genes appear to be isolated from each other, whereas among the controls, three gene pairs (SPINT1 and GMDS, GMDS and TNRC18, and CSNK1D and RNF19B) are connected." (PMID 33596182, 2021).
major depressive disorder (1 paper, 2023). An episode of depression lasting two or more weeks without an intervening episode of mania. "The common genetic characteristics of rheumatoid arthritis and major depressive disorder are EAF1, SDCBP and RNF19B." (PMID 37415981, 2023).
tumor (7 papers, 2012 to 2025). "They contain the granule-associated proteins necessary for tumor killing, including natural killer lytic-associated molecule (NKLAM/RNF19b), an E3 ubiquitin ligase." (PMID 34368150, 2021). "Cul5, Ube2f and Rnf19b were top three hits in both tumor and spleen, while Zgpat, Athl1 and Cisd2 were top three hits in TDLN." (PMID 38242867, 2024).
infection (4 papers, 2018 to 2020). The state of being infected such as from the introduction of a foreign agent such as serum, vaccine, antigenic substance or organism. "Among the infection-specific ISGs upregulated during ΔHA-Cre infection are genes associated with apoptosis (Ripk2, Casp1, Ifi27, Pmaip1) and E3 ubiquitin ligases and proteasome genes, some of which are known to be involved in MHC-I antigen processing (Neurl3, Rnf19b, Psmb9)." (PMID 32790753, 2020).
RNF19B also shares sentences with these, for which no sentence is quoted: melanoma (3 papers); breast carcinoma (2); cancer (2); bacterial infection (1); Cachexia (1); lymphoma (1); myeloid leukemia (1); pneumococcal infection (1); pneumonia (1); rheumatoid arthritis (1); sarcopenia (1); viral infection (1).